DICER1 (dicer 1, ribonuclease III)
Diseases named in the same sentence as DICER1 in open-access papers (continued):
Sharing a sentence is not in itself a finding about the gene and the disease.
tumor (continued). "Consistent with our results, down-regulated expression of Dicer1 has been demonstrated in HCC tissues, compared with the adjacent non-tumor tissues." (PMID 29599909, 2018). "Extensive search of the literature revealed a potential key role of genes at the identified porcine loci in tumor invasion (DST, PLEKHA5, CBY1, LIMK2 and ETV5) and immune response modulation (ETV5, HERC3 and DICER1) of the progression phenotypes." (PMID 29963229, 2018). "Using these models, a recent paper found that haploinsufficient specific deletion of Dicer1 in intestinal epithelial cells promotes tumorigenesis in AOM and DSS induced mouse CRC model, supporting Dicer as tumour suppressor in CRC." (PMID 28915552, 2017). "As expected, we confirmed in individual tumor samples of our patients an inverse correlation of these target mRNA and miR-107 expression levels, being this correlation significant for CCND1, DICER1, DROSHA and NFKB1." (PMID 25197016, 2014). "miRNA biogenesis disorder was promoted by DICER1 destabilization and reintroduction of wild-type TRBP2 inhibited tumor growth and restored miRNA normal synthesis." (PMID 21860617, 2012). "This tumor has an established relation with DICER1 syndrome but does not follow the model of tumor formation like other clinical associations." (PMID 40940982, 2025). "Further analysis showed that tumor mutation burden (TMB) differed significantly between high and low DICER1 expression groups, with a negative correlation between DICER1 expression levels and TMB (R = –0.18, P = 9.4e-08)." (PMID 40666073, 2025). "scRNA-seq of MC38 tumor-bearing mice revealed distinct cell clusters (or subpopulations) within the monocyte/macrophage (“MonoMac”) population, regardless of Dicer1 genotype status." (PMID 40475851, 2025). "Previous studies have shown that thyrocyte-specific deletion of Dicer1 alters follicular structure and function but is not sufficient to initiate tumor development." (PMID 41002430, 2025). "The risk of tumorigenesis has been assessed and by age 10, 5.3% of non-proband DICER1 carriers had developed a neoplasm, whereas by age 50, this percentage is 19.3%." (PMID 40940982, 2025). "A decrease in Dicer1 expression slowed the development of BxPC-1 tumors but increased that of Panc-1 tumors, with no discernible impact on Capan-1 neoplasms." (PMID 39857323, 2025). "Nevertheless, unlike tumor suppressor genes, the double-hit model of DICER1 does not completely abolish protein function, but rather induces altered activity due to hotspot somatic mutations in the RNase IIIb domain." (PMID 40448797, 2025). "This is supported by mouse models: a complete knockout of DICER1 did not lead to tumor formation, but in contrast, led to the inhibition of tumorigenesis." (PMID 40940982, 2025). "In both laboratory settings and living organisms, it was demonstrated that the absence of Dicer1 resulted in elevated characteristics of tumor stemness and aggressiveness." (PMID 38836981, 2024). "However, the DNAm profile of this tumor classified it as RMS-like, a family that is characterized by DICER1 alterations." (PMID 38178234, 2024). "Because this pattern is a hallmark of DICER1-driven neoplasms, the VCEP determined that evidence from somatic tumor sequencing of any DICER1-associated neoplasm, regardless of specificity, should lead to PP4 application if three conditions are met." (PMID 38084291, 2023). "Since DICER1 is a tumor suppressor gene and can inhibit tumor metastasis, we asked whether BART2-5p promoted invasion and metastasis of NPC cells is through suppressing DICER1." (PMID 37495108, 2023). "PRAME overexpression has recently been explored as a potential therapeutic target for immunotherapy in various neoplasms, although not yet in patients with DICER1 LOF." (PMID 38067388, 2023).
tumor (continued). "Our case 9, which had a tumor in the frontal lobe, harbored neither C19MC amplification nor DICER1 mutation and should be classified as ETMR, not elsewhere classified (NEC), according to the 2021 WHO CNS classification." (PMID 36353532, 2022). "While no amplifications were noted in any ERMS of our cohort, one DICER1-wt tumor harbored a somatic deletion including the NF1 locus." (PMID 33846547, 2021). "Due to low tumor cell content in the fourth tumor (ERMS 9) the allelic fraction of the DICER1 alteration was not informative of zygosity." (PMID 33846547, 2021). "Changes included both increased and decreased mRNA expression in the tumor cells, but tilted strongly towards increased expression in the absence of miRNA, suggesting platelet miRNA suppression of tumor transcripts is relieved by Dicer1 deletion." (PMID 34936674, 2021). "We transfected codon-optimized LT (LTco), tumor-derived truncated LT (LT339), and codon-optimized sT (sTco) into MCPyV− MCC cell lines and evaluated the effect on expression levels of DROSHA, DGCR8, DICER1, and TARBP2 using western blotting." (PMID 34761184, 2021). "In a series of 40 adolescent-onset PTC cases, two somatic DICER1 alterations were exclusively detected in each of the two PTC cases that lacked the molecular alterations typical of this tumor type (BRAF, HRAS, KRAS, NRAS, RET, and PAX8)." (PMID 33495912, 2021). "Presence of Dicer1-positive cells is likely attributable to the fact that tumor tissues comprise not only cancer cells but also non-cancer cells, such as endothelial cells, immune cells, and cancer-associated fibroblasts." (PMID 32497036, 2020). "In addition, the expression of DDX5/20, DGCR8, DICER1, DROSHA, EIF2C1-4, GEMIN4, TNRC6A and XPO5 was deregulated not only in tumor tissue, but also in corresponding liver metastases compared to adjacent tissue." (PMID 31510013, 2019). "Repression of DICER1 is not the only oncogenic action of miR-146b, as we have demonstrated that it also represses the tumor suppressor PTEN, leading to an activation of the oncogenic PI3K/AKT pathway." (PMID 30967628, 2019). "AUF1 mRNA level was significantly increased in cancer tissues compared with that in non-tumor tissues, while DICER1 mRNA level in HCC tissues was significantly decreased compared with that in non-tumor tissues." (PMID 29599909, 2018). "Notably, ITGB8, DICER1, INPP5A, PIK3R1, and TIMP2 are key tumor suppressors that were among up-regulated CRGs following CBX2 knockdown." (PMID 26877821, 2016). "Among ACCs (n = 25), DICER1 gene expression did not correlate with survival, probably because the tumor cohort available for gene expression analysis was smaller than for immunohistochemistry." (PMID 26087193, 2015). "DICER1, a known Let-7 target, and RNASEN were over-expressed in C5 tumours." (PMID 21533284, 2011). "Additionally, whereas heterozygous Dicer1 loss did not alter tumor progression in RET/PTC3 mice, total loss reduced tumor growth and led to accumulated DNA damage and cell death." (PMID 41002430, 2025). "We did not confirm the germline origin of the DICER1 mutations in any SLCT; however, in 8 out of the 18 DICER1MUT SLCT germline status could not be assessed as non-tumor tissue was not available for testing." (PMID 39592485, 2025). "Neither the histology, the thyroid-specific and oxidative gene expression profiles or the high percentages of vimentin-positive cells were impacted by Dicer1 inactivation, demonstrating that these changes are attributable to the presence of the tumor itself and not influenced by Dicer1 inactivation." (PMID 41002430, 2025). "The findings of miRNA dysregulation in DICER1 and DGCR8 mutants were consistently supported by the results obtained by analyzing TCGA data from PTCs, suggesting that the mutational effect on miRNA profiles is apparent irrespective of tumor type." (PMID 38252873, 2024).
tumor (continued). "Also, knock-down of DICER1 mRNA in FTC cell lines promotes proliferation in vitro, thereby further strengthening the hypothesis of these miRNA regulators as tumor suppressor genes." (PMID 38252873, 2024). "This strongly supports our hypothesis that the mutational status of DICER1 and DGCR8 rather than tumor histotype determines the global change in miRNA expression." (PMID 38252873, 2024). "In addition, the extensive analysis of TCGA data and our work herein strongly support that DICER1 acts as a tumor suppressor and not an oncogene." (PMID 30967628, 2019). "Interestingly, several tumor samples presented also higher lincRNAs expression and, coincidentally, these tumors tended to have higher (although statistically non-significative) DICER1 expression." (PMID 29459759, 2018). "Finally, the expression of DICER1 and AGO2 is correlated with tumor subtype and may explain some of the changes in miRNA expression observed." (PMID 17922911, 2007). "However, we noted a shift from predominantly cystic or glandular tumor architecture in LGMT DICER1 tumors towards a more cellular mesenchymal morphology with high-grade features and increasing frequency of anaplasia and tumor cell necrosis in high-grade tumors (SARC DICER1 and PIS DICER1)." (PMID 36966138, 2023). "Although a considerable amount of evidence indicates that miR-98 functions as a tumor suppressor, our data, for the first time, revealed that miR-98-5p could induce cisplatin resistance in EOC by suppressing the expression of miR-152 through directly targeting Dicer1." (PMID 29670086, 2018). "By applying unsupervised clustering to our methylation data set we identified outliers, which did not cluster with their tumor group by institutional diagnoses, including one ERMS with DICER1 PVs that was molecularly classified as MAS." (PMID 36966138, 2023). "So, the effects of Dicer1 deletion on proliferation, migration, and invasive properties of TPC1 are not restricted to this particular tumor cell line, as they were reproduced in another tumor cell line (BCPAP) as well as in a non-tumoral cell line (H-Tori3)." (PMID 39409030, 2024). "To determine whether epigenetically regulated miRNAs are tumor-suppressive or not, we evaluated the effect of 5-aza-CdR in siDICER1-transfected KATO-III and DICER1 KO HCT116 (D1KO) cells." (PMID 23667495, 2013). "Finally, there are also several studies describing neither significant difference in the expression of DICER1, DROSHA and EIF2C2 between tumor tissue and adjacent mucosa, nor in the correlation of miRNAs biogenesis genes expression with clinical-pathological features of the patients." (PMID 31510013, 2019).
cancer (234 papers, 2009 to 2026). A tumor composed of atypical neoplastic, often pleomorphic cells that invade other tissues. "Somatic mutations in the Dicer1 gene, especially in the RNase IIIb domain, have been identified in several human cancers, including Wilms tumor, pleuropulmonary blastoma, and others." (PMID 41154621, 2025). "Another known cancer-driver mutation identified in our study is p.E1705K in DICER1, which was detected in a COL sample." (PMID 40867048, 2025). "In the context of a specific cancer, disturbances in DICER1 expression should be considered at multiple levels, including mutations in the DICER1 gene, the level of DICER1 expression, as well as global miRNA expression." (PMID 40127989, 2025). "DICER1 mutations, once thought to be predominantly associated with benign lesions, are now increasingly linked to aggressive cancers in both children and young adults." (PMID 41104964, 2025). "DICER1 tumor predisposition syndrome is a genetic condition that increases the risk of developing certain cancer types." (PMID 40361440, 2025). "These include mutations in DROSHA, DGCR8, and DICER1 in cancer, and recently identified AGO mutations in neurodevelopmental disorders." (PMID 40243428, 2025). "Neither of the mutations identified in our patients (BRAF p.V600E or HRAS p.G13R) has been previously published in DICER1-associated malignancies, despite being bona fide driver mutations in other cancers." (PMID 40634537, 2025). "Mutations in the DICER1 gene were associated with a predisposition to multiple cancer types—the DICER1 syndrome—which is characterized by disrupted miRNA biogenesis and processing with subsequent disruption in the control of gene expression." (PMID 39421690, 2024). "This syndrome influences different benign and malignant tumors characterized by DICER1 loss of function." (PMID 39202414, 2024). "The Cancer Genome Atlas (TCGA) database was also probed for DICER1/DGCR8 mutations and miRNA dysregulation." (PMID 38252873, 2024). "Widely used variant effect prediction tools (CADD, PROVEAN, SIFT, PolyPhen, SNAP, PhD-SNP, and MAPP) were applied to identify missense mutations that are assumed to lead to DICER1-associated cancers." (PMID 39421690, 2024). "Germline pathogenic variants in DICER1 predispose individuals to develop a variety of benign and malignant tumors." (PMID 38084291, 2023). "For example, low or reduced levels of DICER1 or DROSHA mRNA are associated with poor outcomes in human cancers, including lung, breast, skin, endometrial, and ovarian cancers." (PMID 37104009, 2023). "The 12 cancer cases with mutations in the RNase IIIb domain of DICER1 included nine females (75%) with mean age of 13.7 years (SD = 2.0) at surgery." (PMID 36896180, 2023). "Specific mutational signature of XP-C cancers together with high mutation load can favor occurrence of DICER1 mutations leading to gynecological malignancies of XP." (PMID 37567969, 2023). "In contrast, DICER1 hotspot variants are associated with a familial syndrome of cancer predisposition, and only exceptionally occur as somatic changes." (PMID 38067388, 2023). "The identification of DICER1 mutation is notable since it is found in 60% of Sertoli–Leydig cancers, and germline mutations found in Dicer1 increase the possibility of developing rare cancers." (PMID 36900067, 2023). "These somatic missense variations have been identified in nearly all DICER1-associated cancers; they are typically found at five “hotspot” codons in the RNaseIIIb domain (E1705, D1709, G1809, D1810, E1813) and alter the cleavage capacity of the protein." (PMID 37509342, 2023). "In human cancers, mutations in DROSHA, DGCR8, and DICER1 are associated with several types of cancer." (PMID 37179717, 2023). "Although the underlying mechanism is still unclear, transfer RNA-derived fragment biogenesis by DICER1 is directly associated with cancer development." (PMID 36685857, 2022).
cancer (continued). "Differential expressions of DICER1 have been associated with various types and stages of cancers, albeit with contradictory findings." (PMID 35328042, 2022). "Modifications in Dicer1/Ago2 expression result in huge alterations of miRNA expression, which commonly occur in cancer through either germline deletions, mutations, or promoter methylation." (PMID 34721577, 2021). "Imaging-based surveillance for DICER1-associated cancers varies depending on the age of the individual, as the risk for cancers is highest in early childhood and decreases in adulthood." (PMID 33919815, 2021). "We also confirmed the common occurrence of deleterious mutations in SMAD4 and further characterized the specific hotspot mutations in SMAD4, SMAD2 and DICER1, the last group of which were previously reported mostly in childhood cancers." (PMID 33406242, 2021). "Recent studies have shown that Dicer1 required for transfer RNA-derived fragments (tRF) biogenesis is associated with the development of cancer." (PMID 33763118, 2021). "Cancers associated to the DICER1 predisposition syndrome, both benign and malignant, primarily have biallelic loss of function mutations and mutations affecting an RNASE III domain of DICER1." (PMID 32601913, 2020). "In particular, mutations within the RNase IIIb domain of DICER1 markedly reduce the expression of 5p miRNAs (miRNAs derived from the 5′ side of the pre-miRNA) in cancer." (PMID 32138313, 2020). "Among the non-synonymous mutations, 33 were present in both cell line and primary tumor, including truncating mutations of ARID1A and ARID1B genes and a cancer hotspot missense mutation of DICER1 gene (p.D1810Y)." (PMID 33052929, 2020). "On the other hand, these experimental assays validate the unexpected finding that cancer-associated hotspot mutations in DICER1 RNase IIIa and RNase IIIb domains actually have similar biochemical and function consequences." (PMID 31417090, 2019). "Reciprocally, 70% (29/40) of TCGA PanCan and 63% (26/41) of MSK-IMPACT cancer types had zero DICER1 RNase III hotspot mutations (considering only cancer types with sample size >50)." (PMID 31417090, 2019). "Somatic mutations in the RNase IIIb domain of DICER1 arise in cancer and disrupt the cleavage of 5' pre-miRNA arms." (PMID 31417090, 2019). "In summary, comprehensive analyses of DICER1 somatic mutations and small RNA data reveal a mechanistic aspect of pre-miRNA processing that manifests in specific cancer settings." (PMID 31417090, 2019). "We systematically analyzed the landscape of DICER1 hotspot mutations that lead to miRNA strand asymmetries in cancer." (PMID 31417090, 2019). "Compared with the general population prevalence (~1:10,600), the adult cancer cohort (TCGA: ~1:4,600) has trends toward greater frequency of pathogenic DICER1 variation." (PMID 30672147, 2019). "Cell culture and in vitro processing assays established that cancer hotspot mutations in DICER1 RNase IIIb selectively impair miRNA-5p processing." (PMID 31417090, 2019). "Since DICER1 hotspot mutations are overall rare in cancer, we focused on UCEC54, which contained the largest number of DICER1 hotspot mutants." (PMID 31417090, 2019). "This is the largest comprehensive analysis of DICER1 pathogenic variation in adult and pediatric cancer populations using publicly available data." (PMID 30672147, 2019). "In particular, somatic DICER1 mutations, reported in follicular-patterned lesions, are shared by benign as well as malignant tumors." (PMID 30956758, 2019). "Accordingly, cancer hotspot mutant variants of DICER1 exhibit selective defects in processing miRNA-5p strands, leading to overall decreases in 5p:3p strand ratios." (PMID 31417090, 2019). "In this study, we apply our published pathogenicity classification and investigate the prevalence of pathogenic germline (and somatic, when available) DICER1 variants in publicly available genome datasets from cancer cohorts." (PMID 30672147, 2019).